ABCA1 (ATP binding cassette subfamily A member 1)
Diseases named in the same sentence as ABCA1 in open-access papers (continued):
Sharing a sentence is not in itself a finding about the gene and the disease.
astrocytoma (8 papers, 2010 to 2025). "Potency for coactivator recruitment to LXRβ correlated with induction of ABCA1 in human astrocytoma cells." (PMID 41000830, 2025). "We confirmed the CCF-STTG1 astrocytoma cell findings in primary human astrocytes, where we observed a robust induction of both apoE and ABCA1." (PMID 27598782, 2016). "Upon T1317 treatment, the CCF-STTG1 human astrocytoma cell line released cholesterol to exogenously added HEK-apoE3 conditioned media but not to HEK-control vector conditioned media suggesting that apoE is a putative acceptor for ABCA1-mediated cholesterol efflux stimulated by LXR agonists." (PMID 21034469, 2010). "Our data support compound 82879 as a robust inducer of apoE and ABCA1 that validates across two human astrocytic cell types, including CCF-STTG1 astrocytoma cells and more physiologically relevant primary astrocytes from three distinct donors." (PMID 27598782, 2016). "Moreover, the oxysterols 24-OHC, 27-OHC and 25-OHC are able to induce the expression of ABCA1 and ABCG1 transporters in U-87 MG astrocytoma cells; among the three oxysterols, 24-OHC was found to be the most potent." (PMID 34943002, 2021). "Moreover, being a natural endogenous agonist of LXRs, 24-OHC up-regulates the expression of the LXR target genes coding for ABCA1, ABCG1 and ApoE, all key regulators of cellular cholesterol homeostasis, as demonstrated in primary astrocytes and in astrocytoma cells." (PMID 34943002, 2021). "The LRP-1 and ABCA-1 mRNA expression of the GBM cases was significantly higher than the normal brain/non-tumor tissue and lower-grade astrocytomas." (PMID 36267880, 2022). "To extend our studies beyond CCF-STTG1 astrocytoma cells (APOE3/APOE4), we next verified the apoE and ABCA1 activities of compound 82879 in non-transformed primary human astrocytes from three donors genotyped as APOE3/E3 or APOE3/E4." (PMID 27598782, 2016).
cerebral malaria (8 papers, 2012 to 2024). A sequestration of Plasmodium falciparum in the brain, which can cause coma and/or seizures. "After MVs were found in dramatically elevated numbers in cerebral malaria patients, the finding that the ABCA-1 knock-out fully protected mice against cerebral malaria pointed towards a pathogenic role for MVs." (PMID 31877909, 2019). "The role of ABCA1 in microvesicle formation seems to be relevant in the pathogenesis of cerebral malaria." (PMID 33562440, 2021). "Because miR-27a was found to inhibit ABCA1 expression in vitro, to abolish microvesicle production and inhibit apoptotic mechanisms, this miRNA has been proposed as protective against cerebral malaria." (PMID 33562440, 2021). "A role for MV overproduction in disease pathogenesis was further substantiated by the finding of a complete protection against cerebral malaria in ABCA1 knock-out mice." (PMID 31877909, 2019). "ABCA1 knockout mice, which have a lower ability to produce EVs, can significantly reduce the inflammatory response and relieve the severity of cerebral malaria." (PMID 30697211, 2018). "In a murine model of cerebral malaria, ABCA1 deletion resulted in significantly less pathology due to both decreased inflammation and microparticle circulation." (PMID 27462310, 2016). "Abca1-/- mice survive cerebral malaria after P. berghei ANKA infection and have significantly lower levels of TNFα than wild-type mice." (PMID 26599510, 2015). "Abca1-/- mice have fewer pro-inflammatory microparticles in plasma and, decreased brain TNFα compared with wild-type littermates, and are protected from cerebral malaria." (PMID 26599510, 2015). "ABCA1 knockout mice showed decreased PS externalization, as well as low circulating MP levels, which led to their complete resistance to cerebral malaria." (PMID 24860829, 2014). "In a mouse model, they demonstrated that ABCA1, a membrane transporter regulating the transbilayer distribution of PS at the outer leaflet of the plasma membrane, contributes to the pathogenesis of cerebral malaria by affecting MP shedding." (PMID 24860829, 2014). "Additionally, the ABCA1 transporter participates in infectious and/or thrombotic disorders involving vesiculation, since homozygous ABCA1 gene deletions confer complete resistance against cerebral malaria in mice." (PMID 22768049, 2012). "Abca1 KO mice showed lower plasma concentrations of microvesicles, and when infected with Plasmodium berghei ANKA, these mice show complete resistance to cerebral malaria." (PMID 33562440, 2021).
lung adenocarcinoma (8 papers, 2018 to 2026). A carcinoma that arises from the lung and is characterized by the presence of malignant glandular epithelial cells. "In a specific study, Xu and his research team investigated the mechanism through which the interaction between IGF2BP1 and ABCA1 contributes to the progression of lung adenocarcinoma." (PMID 41303341, 2025). "This regulatory effect on ABCA1 expression further impacts the molecular mechanisms governing cholesterol metabolism and, in turn, promotes the malignant progression of lung adenocarcinoma." (PMID 41303341, 2025). "However, in human lung adenocarcinoma cells, NC efficacy was inversely correlated with the expression level of the drug transporter ABCA1: cancer cells with downregulated ABCA1 were more sensitive to NC treatment." (PMID 41521893, 2026). "Decreased ABCA1 expression in several cancers, such as prostate, breast, and oral cancers, is associated with the rate of cancer cell proliferation, and ABCA1 overexpression substantially inhibits the proliferation, migration, and invasion of lung adenocarcinoma cells." (PMID 36672209, 2023). "We therefore hypothesized that PPARG, LXRα, and ABCA1 were related to tumor‐suppressive effects against acquired gefitinib‐resistant lung adenocarcinoma cells, and efatutazone, the novel third‐generation PPARG agonist, could be a potentially useful choice for patients with lung adenocarcinoma." (PMID 29573196, 2018). "In the process of initiation and development of lung adenocarcinoma, the expressions of PPAR, LXR, and ABCA1 were decreasing." (PMID 29573196, 2018). "In addition, combination of efatutazone and LXRα agonist T0901317 showed a synergistic therapeutic effect on lung adenocarcinoma cell proliferation and PPAR gamma, LXR A and ABCA1 protein expression." (PMID 29573196, 2018).
myocardial infarction (8 papers, 2016 to 2024). Gross necrosis of the myocardium, as a result of interruption of the blood supply to the area, as in coronary thrombosis. "Interestingly, despite the atheroprotective role of Abca1, it has been shown to adversely affect cardiac function after myocardial infarction in mice." (PMID 36011386, 2022).
gastric cancer (7 papers, 2022 to 2025). A primary or metastatic malignant neoplasm involving the stomach. "The results showed that ABCA1 was closely associated with multiple clinical features, immune infiltration, and drug sensitivity in gastric cancer patients." (PMID 36713557, 2022). "However, there are few reports of ABCA1 being associated with gastric cancer." (PMID 36713557, 2022). "By combining TCGA,GTEx and GEO data sets, we found that ABCA1 expression was significantly up-regulated in gastric cancer tissues compared with normal gastric tissues." (PMID 36713557, 2022). "ABCA1 was identified as a key gene in LDMRGs and multi-omics analysis showed a strong correlation between ABCA1 and the prognosis and immune status of patients with gastric cancer." (PMID 36713557, 2022). "Finally, we identified the key gene in LDMRGs, ABCA1, and performed a systematic multi-omics analysis in gastric cancer." (PMID 36713557, 2022). "Our study demonstrated that ABCA1 was closely related to the prognosis and immune regulation of patients with gastric cancer and could potentially be a new therapeutic target for gastric cancer." (PMID 36713557, 2022). "In addition, we explored that patients with gastric cancer in the ABCA1 high expression group had a worse prognosis in the TCGA-STAD cohort, the GSE15459 cohort and the GSE26253 cohort." (PMID 36713557, 2022). "Finally, we identified a key gene in LDMRGs, ABCA1, and analyzed the prognostic value of ABCA1 in gastric cancer by multi-omics." (PMID 36713557, 2022). "We speculated that ABCA1 may be involved in the invasion and metastasis of gastric cancer through the PI3K-Akt signaling pathway." (PMID 36713557, 2022). "Mechanistically, PUF60 enhances chemotherapy resistance in gastric cancer (GC) cells by actively excluding chemotherapy drugs via the recombinant ATP Binding Cassette Transporter A1 (ABCA1) and ATP Binding Cassette Subfamily C Member 1 (ABCC1)." (PMID 39781520, 2025).
Parkinson disease (7 papers, 2020 to 2025). A progressive degenerative disorder of the central nervous system characterized by loss of dopamine producing neurons in the substantia nigra and the presence of Lewy bodies in the substantia nigra and locus coeruleus. "In Parkinson’s disease, ABCA1 is thought to modulate glial inflammation and lipid homeostasis, although evidence remains more limited." (PMID 41602910, 2025). "Results of KEGG pathways depicted the top pathways that ABCA1 participated in, including oxidative phosphorylation, Parkinson’s disease, and infection." (PMID 37749600, 2023). "The present study is aimed at investigating the effects of miR-873 on cholesterol homeostasis via ABCA1 and progressive DA neuron damage using a LPS-induced neuroinflammatory model of Parkinson's disease." (PMID 32724496, 2020). "It was reported before that hsa-miR-144-3p and hsa-miR-144-5p regulate ABCA1 and ATP6V1C1 (Capstone Project: Data Science DSC180B; Genetic Overlap between Alzheimer’s, Parkinson’s, and healthy patients; replication project for the paper)." (PMID 37822091, 2023).
type 1 diabetes (7 papers, 2013 to 2023). "Only the role of ABCA1 has previously been examined in mouse models of type 1 diabetes and renal expression of ABCA1 was reduced." (PMID 25181357, 2014). "Cholesterol efflux from J774A.1 macrophages to glycated lipid-free apoA-I via ABCA1 or glycated drHDL via an ABCG1-dependent mechanism was unaltered, as was efflux to minimally modified apoA-I from people with Type 1 diabetes, or controls." (PMID 23741493, 2013).
viral infection (7 papers, 2020 to 2024). "Membrane cholesterol content and ATP-binding cassette transporter A1 (ABCA1) expression have been shown to be closely related to susceptibility to viral infection." (PMID 38257890, 2023). "ABCA1 deficiency induced by HCV might enhance viral infection." (PMID 34492079, 2021). "RT-qPCR and immunoblotting indicated that HSV-1 decreased both the mRNA and protein levels of ABCA1 and ABCG1, whereas this decrease was restored by RA supplementation, thus suggesting that viral infection inhibited RA synthesis and consequently prevented ABCA1/G1-mediated lipid efflux." (PMID 38989466, 2024). "Expression of ABCA1 and RIP140 implicated in lipid metabolism, a mechanism which has been shown to play a role in viral infections on the other hand did not significantly change in patients with SD." (PMID 31954402, 2020). "Finally, although cholesterol metabolism has been found to be altered in other viral infections such as dengue and chikungunya, the direct participation of ABCA1 in these diseases has not been demonstrated." (PMID 33562440, 2021).
Cerebral ischemia (6 papers, 2017 to 2024). Restriction of arterial blood supply to the brain associated with insufficient oxygenation to support the metabolic requirements of the tissue. "Abca1 is closely linked to the regulation of efferocytosis after cerebral ischemia and is specifically expressed in microglia." (PMID 39223647, 2024). "Increased ABCA1 expression following IPC exerts a protective influence against cerebral ischemia via suppression of a mitochondria-dependent apoptosis pathway." (PMID 34131232, 2021). "In conclusion, increased ABCA1 expression following IPC exerts a protective effect against cerebral ischemia via suppression of a mitochondria-dependent apoptosis pathway." (PMID 34131232, 2021). "Further, it is noteworthy that ABCA1 has been identified as a regulator of astrocytic phagocytosis in cerebral ischemia." (PMID 34233703, 2021). "We demonstrated that adult astrocytes can function as phagocytes in a restricted spatiotemporal pattern after transient brain ischemia, and ABCA1 and its related pathway molecules play indispensable roles in this mechanism." (PMID 28642575, 2017). "In conclusion, we demonstrated that astrocytes become phagocytic after brain ischemia, and ABCA1 and its pathway molecules play a pivotal role in this process." (PMID 28642575, 2017). "Here the authors show that following brain ischemia, reactive astrocytes become phagocytic and engulf debris via the ABCA1 pathway." (PMID 28642575, 2017).
cognitive decline (6 papers, 2015 to 2025). "Impaired ABCA1 function (due to polymorphisms or downregulation in disease states) leads to reduced ApoE lipidation, diminished Aβ clearance, and increased Aβ and tau pathology, and accelerates cognitive decline." (PMID 41226793, 2025). "The underlying mechanism for the different associations between ABCA1 R219K polymorphism and cognitive decline remains unclear." (PMID 28824418, 2017). "In addition, ABCA1 promotes cholesterol efflux to the cerebrospinal fluid, thereby improving cognitive decline in AD patients." (PMID 32636753, 2020).
Hyperinsulinemia (6 papers, 2015 to 2022). An increased concentration of insulin in the blood. "Hyperinsulinism was associated with ER stress, metainflammation, and a compensatory response of ABCA1 overexpression." (PMID 36005626, 2022). "Sealls and colleagues demonstrated that Cr3+ reversed hyperinsulinemia-induced cellular cholesterol accrual and associated defects in cholesterol transporter ABCA1 trafficking and apolipoprotein A1-mediated cholesterol efflux." (PMID 30723735, 2019). "Examination of ABCA1 trafficking revealed that the presence of chromium could prevent the decrease of plasma membrane ABCA1 by hyperinsulinemia conditions relevant to onset of disease." (PMID 37073221, 2022). "Auraptene treatment ameliorated hyperinsulinism coupled with high ABCA1 levels, which maintained cholesterol homeostasis; therefore, the activity of cholesterol transport and the inhibition of cholesterol esterification through ACAT1 could play a significant protective role." (PMID 36005626, 2022).
lung diseases (6 papers, 2005 to 2025). "An increasing number of studies indicate that ABCA1 is not only associated with cardiovascular disease, but may also be involved in the occurrence and development of lung diseases." (PMID 40808841, 2025). "Moreover, abnormal function of ABCA1 may also affect lung inflammation response and immune regulation, thereby increasing susceptibility to lung diseases." (PMID 40808841, 2025). "It was indeed reported that both Abca1 -/- and Abcg1-/- mice accumulate lipids into T2P cells exhibit an age-related progressive pulmonary disease, including lipidosis and chronic inflammation." (PMID 38970705, 2024). "Evidence from both in vitro and in vivo studies have shown ABCA1 expression is altered in lung diseases such as COPD." (PMID 32977800, 2020). "Recent investigations have revealed that a number of inflammatory mediators and noxious exposures (such as cigarette smoke) that drive lung disease also have an impact on ABCA1 expression." (PMID 32977800, 2020). "Many studies have demonstrated a protective role for an apoA-I/ABCA1 pathway in the pathogenesis of lung disease." (PMID 28521806, 2017). "The possible role of ABCA1 in ILD is unknown and there are no reports on ABCA1 mutations associated with lung disease in humans." (PMID 15819986, 2005).
renal clear cell carcinoma (6 papers, 2021 to 2025). "In agreement, CYP27A1 was found to inhibit proliferation and migration of clear cell renal cell carcinoma by activating the LXRs/ABCA1 pathway." (PMID 37210507, 2023). "Celastrol also induces lipophagy via the activation of the liver-X receptors α (LXRα)/ATP-binding cassette transporter A1 (ABCA1) pathway in clear cell renal carcinoma." (PMID 34575981, 2021). "In addition, celastrol exerts pronounced renal lipophagy-regulatory efficacy by inducing lipophagy in clear cell renal cell carcinoma via liver X receptor α (LXRα)/ATP-binding cassette transporter A1 (ABCA1) pathway activation." (PMID 41050400, 2025). "There are few data on the effect of ABCA1 on renal clear cell carcinoma." (PMID 40297807, 2025). "However, most of the current data show that ABCA1 is related to the proliferation, invasion and metastasis of cancer, but whether ABCA1 affects the prognosis of cancer patients by affecting the development of renal clear cell cancer cells needs further exploration." (PMID 40297807, 2025). "By analysing the results, we found a correlation between low expression of ABCA1 and poor OS (P = 0.00025) and DFS (P = 0.025) in renal clear cell carcinoma patients." (PMID 40297807, 2025). "In addition, a recent article reported that ABCA1 was less expressed in renal clear cell carcinoma tissues than in adjacent tissues, and the overexpression of ABCA1 upstream LXR-α could trigger autophagy and ABCA1-mediated cholesterol efflux, ultimately inhibiting tumor growth." (PMID 38481816, 2024).
retinal degeneration (6 papers, 2019 to 2024). Degeneration of the retina. "Cholesterol recycling, particularly via Abca1, is required to maintain retinal function and the disruption of this pathway leads to retinal degeneration." (PMID 36291646, 2022). "ApoE transports cholesterol in association with ABCA1, another protein implicated in AMD, and RPE-specific deletion of ABCA1 in mice causes RPE cholesterol storage and progressive RPE atrophy, photoreceptor loss, and retinal degeneration." (PMID 33822768, 2021). "In mice, the selective loss in the RPE of ABCA1, coding for the lipid transporter ABCA1, causes lipid accumulation in the RPE, retinal inflammation, and RPE and retina degeneration, indicating the crucial role of lipid handling by RPE cells, for their own and retinal viability." (PMID 38786093, 2024). "Targeting the deletion of cholesterol efflux genes, such as Abca1 and Abcg1, promoted the formation of drusen-like lesions and finally resulted in retinal degeneration with age, which seems to support the hypothesis that drusen cause AMD." (PMID 38731137, 2024). "Studies show that the knock-out of Abca1 in the retinas of mice leads to retinal degeneration." (PMID 36291646, 2022). "Genetic variants in ABCA1 are also implicated in AMD, and mouse models with RPE-specific deletion of ABCA1 show RPE atrophy and retinal degeneration." (PMID 33822768, 2021). "A mouse model lacking ABCA1 and ABCG1 showed lipid accumulation, retinal degeneration, and inflammation." (PMID 37587376, 2024).